TAF6 (TATA-box binding protein associated factor 6)
Description:
The TFIID basal transcription factor complex plays a major role in the initiation of RNA polymerase II (Pol II)-dependent transcription. TFIID recognizes and binds promoters with or without a TATA box via its subunit TBP, a TATA-box-binding protein, and promotes assembly of the pre-initiation complex (PIC). The TFIID complex consists of TBP and TBP-associated factors (TAFs), including TAF1, TAF2, TAF3, TAF4, TAF5, TAF6, TAF7, TAF8, TAF9, TAF10, TAF11, TAF12 and TAF13. The TFIID complex structure can be divided into 3 modules TFIID-A, TFIID-B, and TFIID-C. TAF6 homodimer connects TFIID modules, forming a rigid core. [Isoform 4]: Transcriptional regulator which acts primarily as a positive regulator of transcription. Recruited to the promoters of a number of genes including GADD45A and CDKN1A/p21, leading to transcriptional up-regulation and subsequent induction of apoptosis. Also up-regulates expression of other genes including GCNA/ACRC, HES1 and IFFO1. In contrast, down-regulates transcription of MDM2. Drives apoptosis via the intrinsic apoptotic pathway by up-regulating apoptosis effectors such as BCL2L11/BIM and PMAIP1/NOXA.
Synonyms: TAF(II)70; TAFII-70; TAFII70; TAF(II)80; TAFII-80; TAFII80; TAF2E; MGC:8964; TAFII85; ALYUS
Tractability: Small molecule: a structure with a bound ligand is known. PROTAC: UniProt records ubiquitination sites on it; ubiquitination databases record sites on it; its protein half-life has been measured.
Gene: Protein-coding gene on chromosome 7 (100,106,876 to 100,120,091, reverse strand). Ensembl gene ENSG00000106290.
Subcellular location: Nucleus; Nucleus (Isoform 4)
Subcellular location (Human Protein Atlas): Nucleoplasm; Cytosol
Pathways (Reactome):
Gene expression (Transcription): RNA Polymerase II Pre-transcription Events; RNA Polymerase II Promoter Escape; RNA Polymerase II Transcription Initiation; RNA Polymerase II Transcription Initiation And Promoter Clearance; RNA Polymerase II Transcription Pre-Initiation And Promoter Opening; RNA polymerase II transcribes snRNA genes
Disease: HIV Transcription Initiation; RNA Polymerase II HIV Promoter Escape; Transcription of the HIV genome
Gene Ontology:
Molecular function: aryl hydrocarbon receptor binding; DNA binding; protein binding; RNA polymerase II general transcription initiation factor activity; transcription coactivator activity; protein heterodimerization activity
Biological process: DNA-templated transcription initiation; mRNA transcription by RNA polymerase II; negative regulation of cell cycle; positive regulation of transcription initiation by RNA polymerase II; regulation of transcription by RNA polymerase II; RNA polymerase II preinitiation complex assembly; transcription initiation at RNA polymerase II promoter; positive regulation of DNA-templated transcription; regulation of DNA repair; transcription by RNA polymerase II
Cellular component: MLL1 complex; nucleoplasm; nucleus; protein-containing complex; transcription factor TFIID complex; transcription factor TFTC complex; SAGA complex; SLIK (SAGA-like) complex
Genetic constraint (gnomAD): Loss-of-function variants: 47 observed, 72.52 expected, observed/expected ratio (o/e) 0.65, 90% interval 0.51 to 0.83. The upper end of that interval is the gene's LOEUF score, 0.83, which puts it in group 3 of 6, group 1 being the genes least tolerant of losing a copy. Missense variants: 750 observed, 906.32 expected, observed/expected ratio (o/e) 0.83, 90% interval 0.78 to 0.88. Synonymous variants: 418 observed, 378.96 expected, observed/expected ratio (o/e) 1.1, 90% interval 1.02 to 1.2.
Homologues: Orthologues: chimpanzee TAF6 (99% identical), macaque TAF6 (99% identical), dog TAF6 (98% identical), pig TAF6 (98% identical), guinea pig TAF6 (98% identical), mouse Taf6 (97% identical), rat Taf6 (97% identical), rabbit TAF6 (95% identical), tropical clawed frog taf6 (72% identical), zebrafish taf6 (68% identical), Drosophila melanogaster Taf6 (42% identical). Paralogues in human: TAF6L (22% identical).
Diseases named in the same sentence as TAF6 in open-access papers:
TAF6 is named in the same sentence as 22 diseases in open-access papers, as found by Europe PMC text mining. Sharing a sentence is not in itself a finding about the gene and the disease. The quoted sentences say what the papers report.
Intellectual disability (2 papers, 2024 to 2025). "A homozygous TAF6 variant was identified in a female patient with intellectual disability, ASD, muscular hypotonia, and cerebellar hypoplasia likely impairing neuronal gene expression." (PMID 40558542, 2025).
leukemia (2 papers, 2022 to 2023). A malignant (clonal) hematologic disorder, involving hematopoietic stem cells and characterized by the presence of primitive or atypical myeloid or lymphoid cells in the bone marrow and the blood. "In the leukemia cell line HL-60 with the NRASQ61L mutation and the pancreatic cancer cell line MIA PaCa-2 with the KRASG12C mutation, the mRNA expression of DOHH, HIST1H2AC, and TAF6 were measured with MEK-I treatments." (PMID 36358254, 2022).
breast carcinoma (1 paper, 2008). "In this light, it is intriguing that expression levels of TAF6 have been correlated with the inflammatory breast cancer phenotype, and isoform specific enrichment of a TAF6 splicing variant has been reported in breast cancer." (PMID 18628956, 2008).
hepatoma (1 paper, 2022). "We analyzed the expression of TAF6 in normal hepatocytes and hepatoma cell lines, and the results of real-time quantitative PCR indicated that TAF6 expression was significantly higher in hepatoma cell lines than in normal hepatocytes." (PMID 36248822, 2022).
inflammatory breast carcinoma (1 paper, 2014). An advanced, invasive breast adenocarcinoma characterized by the presence of distinct changes in the overlying skin. "TAF6 mRNA was identified as being overexpressed in inflammatory breast cancer." (PMID 25025302, 2014).
liver cancer (1 paper, 2022). An epithelial or non-epithelial malignant neoplasm that arises from the liver. "including HepG2,SMCC7721,MHCC97H,Huh-7 and HCCLM3.As shown in, compared with HL7702 (normal liver cells), TAF6 was expressed at relatively higher levels in liver cancer cell lines." (PMID 36248822, 2022). "IHC results showed that TAF6 was highly expressed in liver cancer." (PMID 36248822, 2022). "In addition, we assessed the expression level of TAF6 in the cell lines in liver cancer cell lines." (PMID 36248822, 2022).
lung adenocarcinoma (1 paper, 2014). A carcinoma that arises from the lung and is characterized by the presence of malignant glandular epithelial cells. "TAF6 has been reported as a genomic marker of poor prognosis in lung adenocarcinoma." (PMID 25025302, 2014).
lung carcinoma (1 paper, 2014). "Integrative genomic data show that the taf6 gene is amplified in lung cancer." (PMID 25025302, 2014).
melanoma (1 paper, 2016). A malignant, usually aggressive tumor composed of atypical, neoplastic melanocytes. "More specifically, TAFH RNAi in melanoma cells led to the high levels of TAF6_v3 encoding the protein isoform with altered histone fold domains (HFD) similar to the apoptosis-dependent form of TAF6, namely TAF6δ46." (PMID 27499390, 2016). "In melanomas, TAFH RNAi induced the differential expression of TBP, TAF1, TAF2, TAF6, TAF10, and TAF12 ASVs." (PMID 27499390, 2016).
microcephaly (1 paper, 2023). A congenital or acquired developmental disorder in which the circumference of the head is smaller than normal for the person's age and sex. "In individuals with diseases previously related to the TAF6 and AP4M1 genes, some of the clinical features observed include reduced growth, including microcephaly." (PMID 38254912, 2023).
osteosarcoma (1 paper, 2008). A usually aggressive malignant bone-forming mesenchymal neoplasm, predominantly affecting adolescents and young adults.
Sepsis (1 paper, 2021). Sepsis is defined as life-threatening organ dysfunction caused by a dysregulated host response to infection. "Furthermore, we explored the underlying mechanism of TAF6/NF-κB pathway in sepsis-induced myocardial damage." (PMID 34489703, 2021).
thyroid cancer (1 paper, 2024). "Thus, although, for the investigated thyroid tissue, both POLR2B and TAF6 might be used as housekeeping genes, they are not suitable as references for cultured thyroid cancer cells." (PMID 38790250, 2024).
Tinnitus (1 paper, 2023). Tinnitus is an auditory perception that can be described as the experience of sound, in the ear or in the head, in the absence of external acoustic stimulation. "Interestingly, the TAF6 gene was also enriched in missense variants in a Swedish cohort, composed of 147 patients with chronic and constant tinnitus." (PMID 38254912, 2023). "We report four CNVs in patients with MD and severe tinnitus: three rare deletions in the ERBB3 gene, and a large duplication involving AP4M1, COPS6, MCM7, and TAF6." (PMID 38254912, 2023).
cancer (6 papers, 2014 to 2025). A tumor composed of atypical neoplastic, often pleomorphic cells that invade other tissues. "The essential nature of TAF6 therefore underscores the strategic value in exploring this pathway as a therapeutic target in cancer, since its expression cannot be extinguished to generate resistance." (PMID 29358700, 2018). "Interestingly, while the expression control of TAF6 increased in Φ, it stayed practically the same in T (ΔREC = 5), but decreased in Θ (ΔREC = −46), indicating significant changes in cancer cells’ priorities for controlling the expression fluctuations of this gene." (PMID 38790250, 2024). "Our anti-TAF2 antibody was able to immunoprecipitate endogenous TAF2, as well as core subunits of the TFIID complex, including TBP, TAF4, TAF5, TAF6, and TAF7, in nuclear extracts from colorectal HCT116, embryonic kidney HEK-293, and ovarian A2780 cancer lines." (PMID 38773077, 2024). "On the other hand, the much stricter control of TAF6 in the BCPAP cells while being looser in the 8505C cells and practically not affected in the surgically removed cancer specimen may indicate different anti-tumor molecular mechanisms." (PMID 38790250, 2024).
tumor (5 papers, 2008 to 2025). "The analysis of TCGA data showed that, CFHR4, DNASE1L3, and SPP2 were significantly higher in adjacent non-tumor tissues, while TAF6 was upregulated in HCC tissues." (PMID 36248822, 2022). "Furthermore, targeting TAF6 results in a substantially more robust apoptotic response than targeting another apoptotic gene, Bcl-x in several tumor cell lines." (PMID 18628956, 2008). "It is interesting to note that POLR2B was up-regulated in both cell lines, but not in the tumor (x(T) = 1.15; x(Φ) = 74.40; x(Θ) = 80.06), while TAF6 was down-regulated in both cell lines, but not in the tumor (x(T) = −1.02; x(Φ) = −1.91; x(Θ) = −3.24)." (PMID 38790250, 2024). "The real-time quantitative PCR results showed that CFHR4, SPP2, and DNASE1L3 were expressed higher in non-tumor tissues (Non-Tumor) than in tumor tissues (Tumor), and TAF6 was expressed higher in tumor tissues than in non-tumor tissues." (PMID 36248822, 2022).
TAF6 also shares sentences with these, for which no sentence is quoted: autism spectrum disorder (1 paper); ciliopathies (1); Cirrhosis (1); gastric cancer (1); liver disease (1); pancreatic cancer (1).